SIRT1 (sirtuin 1)
Diseases named in the same sentence as SIRT1 in open-access papers (continued):
Sharing a sentence is not in itself a finding about the gene and the disease.
cancer (continued). "Furthermore, SIRT1 inhibition affects key phenotypic aspects of cancer cells." (PMID 16596166, 2006). "Interestingly, the recent report that cancer cells have increased overall levels of deacetylation of the known histone target of SIRT1, H4-K16, could well be related to the findings we now report at localized regions of aberrantly silenced TSGs." (PMID 16596166, 2006). "This review summarizes recent advances in understanding how SIRT1 and SIRT2 coordinate tumor metabolism and discusses therapeutic strategies that target their regulatory balance to reprogram cancer metabolism." (PMID 41800243, 2026). "Sirtuin 1 (SIRT1) and Sirtuin 2 (SIRT2) are NAD+-dependent deacetylases that regulate cancer metabolic stress, exerting their effects primarily through post-translational modification of metabolic enzymes and transcription factors." (PMID 41800243, 2026). "Contextual dependency defines their activity: SIRT1 and SIRT5, for example, suppress or stimulate glycolysis based on the cancer type and metabolic stress." (PMID 41425553, 2025). "The expression levels of Sirt1 in GBM have been debated, but its crucial role in various cancers is widely acknowledged." (PMID 40075208, 2025). "SIRT1, a NAD+-dependent deacetylase, is involved in glucose metabolism, fatty acid oxidation, and mitochondrial function in cancer cells." (PMID 41278473, 2025). "In cancer cells, the NAD+–SIRT1 signaling pathway contributes to tumor survival by regulating redox homeostasis and suppressing cellular senescence." (PMID 41008982, 2025). "SIRT1 also influences the Warburg effect by inhibiting HIF-1α, which is necessary for the metabolic shift to glycolysis in cancer cells." (PMID 41436543, 2025). "miR-34a mediates cell signaling pathways dependent on cancer cell apoptosis including: EGFR, PDGFR-α/β, MET, SIRT1, NOTCH1, BCL2, and HMGB1." (PMID 40061926, 2025). "SIRT1 and SIRT2 are pivotal in cell metabolism, inflammation, aging, cardiovascular diseases, neurodegenerative disorders, and cancer." (PMID 40563894, 2025). "Simultaneously, SIRT1-mediated activation of the CD24/Siglec-10 axis suppresses the activity of CD8+ T cells, crucial immune cells responsible for targeting and killing cancer cells." (PMID 40330466, 2025). "The sirtuin family consists of seven members (SIRT1 to SIRT7), with SIRT1 being a key regulator of various cellular pathways, including energy metabolism, stress responses, senescence, cancer, and longevity." (PMID 40006932, 2025). "Immunosuppression, as a result of SIRT1 and SIRT3 activation, can reduce immune surveillance, thereby promoting cancer progression." (PMID 40673471, 2025). "Silent information regulator type 1 (SIRT1), a NAD+-dependent deacetylase, is a central regulator of cancer cell adaptation to oxidative stress and senescence." (PMID 41008982, 2025). "Distinct cancers rely on unique regulatory circuits: for instance, HCC frequently engages SIRT1–p62 or PCAF–microtubule pathways, whereas breast cancer emphasizes p300/CREBBP-driven stabilization of transcription factors (e.g., HOXB13, RB1CC1)." (PMID 41213956, 2025). "In this context, the overexpression of Sirtuin 1 (SIRT1), a NAD+-dependent deacetylase, has been shown to play an oncogenic role in various cancer types, including AML." (PMID 40806596, 2025).
cancer (continued). "NNMT should thus be regarded not as a solitary oncogenic effector but as a pivotal metabolic checkpoint that indirectly regulates SIRT1 activity, positioning it at the intersection of NAD+ and SAM metabolism in cancer." (PMID 41008982, 2025). "Important biological functions required for the proliferation of cancer cells, such as “transcription, cell-cycle progression, anti-apoptosis, and DNA repair,” are regulated by NAD-dependent enzymes like SIRT1." (PMID 40439888, 2025). "Sirtuins, or 'longevity proteins', a family of 7 proteins (SIRT1 – SIRT7), are involved in skin pathology, including aging, UV-induced photoaging, and cancer." (PMID 40290806, 2025). "Mechanistically, UA induced cell cycle arrest and apoptosis while enhancing the expression of key tumor suppressors, including Sirtuin 1 (Sirt1) and Forkhead box protein O1 (FOXO1), both of which are crucial regulators of cancer cell dynamics." (PMID 40568370, 2025). "Higher SIRT1 expression was observed mainly in 76% of grade I, 34% of grade II, and 50% of grade III carcinomas." (PMID 39858444, 2025). "Elevated SIRT1 expression inhibits the AIM2 inflammasome, a mechanism that suppresses pyroptosis while promoting the proliferation of cancer cells." (PMID 38474460, 2024). "Our research results demonstrate that SIRT1 and FOXO3 can regulate mitophagy in EC cells, which differs slightly from reports in other cancers." (PMID 39266959, 2024). "For instance, FOXO3 can also be deacetylated by SIRT1, and it collaborates with FOXK2 to regulate the apoptosis of cancer cells." (PMID 38741782, 2024). "One of the most extensively studied functions of hCCAR2 is its inhibition of SIRT1, an NAD+-dependent deacetylase that regulates various processes, such as apoptosis, stress responses, metabolism, longevity, and cancer-related processes." (PMID 38172598, 2024). "Selisistat blocks protein-protein interactions between breast cancer deletion 1 (DBC1) and SIRT1 through an acetylation-independent mechanism." (PMID 39479446, 2024). "Taken together, miR-34a is an important regulator of leukemogenesis through different mechanisms including inhibition of CDK4, MYB, and SIRT1 expression, and/or suppression of B-Myb and E2F1 expression, leading to cell cycle arrest in cancer cells." (PMID 38361758, 2024). "Calycosin activates the SIRT1/AMPK axis to inhibit the Akt/mTOR pathway, stimulating autophagy-mediated apoptosis in cancer cells." (PMID 39403142, 2024). "Here, we report the first evidence that SIRT1 is regulated by miR-181c/d in BTC and to a greater extent in cancer." (PMID 38598008, 2024). "Although SIRT1 has been studied in cancer research in recent decades, the role of SIRT1 in cancer has remained controversial, likely due to the genetic background of cancer, type of tissue, stage of cancer, and distinct regulation of SIRT1, which might differentially affect substrates." (PMID 38443596, 2024). "By contrast, associations of dasatinib sensitivity with stronger upregulation of SIRT1, SIRT2, and SIRT5 were unexpected, since these genes have tumour promoting effects, and their downregulation positively affects cancer treatment outcomes." (PMID 38369747, 2024). "In our study on EC cells, we observed significant alterations in the expression levels of SIRT1 and FOXO3, consistent with reports in other cancer types." (PMID 39266959, 2024). "Specifically, HDAC4, HDAC5, KAT2B, NCOA1, SIRT1, and SIRT4 had lower expression in tumor tissues across 14, 12, 18, 17, 16, and 12 cancer types, respectively." (PMID 39906742, 2024). "Oleuropein exhibits a more variable profile; it can either decrease levels of tumor suppressors like SIRT1 or alter oncogene expressions such as KRAS and mTOR, depending on the cancer type." (PMID 39203892, 2024).
cancer (continued). "The new compounds were tested against SIRT1 and SIRT2 and evaluated for their cytotoxic activities against a panel of nine cancer cell lines." (PMID 38794171, 2024). "Sirt1, a key target in the NAD+-dependent protein deacetylase family, is involved in aging, metabolism, cancer, stress responses, and the biological clock." (PMID 39335583, 2024). "While other sirtuins, such as SIRT1 and SIRT6, exhibit a similar dual role in cancer, SIRT7 stands out due to distinctive attributes that sharply distinguish it from other family members." (PMID 38383727, 2024). "Among these core genes, all except H3C12 were closely related to cancers (KIRC and LGG), in which SIRT1 expression affected prognosis." (PMID 39845948, 2024). "BZD9L1 is a SIRT1 and SIRT2 inhibitor reported to down-regulate SIRT1 and SIRT2 gene and protein expression in healthy and cancer models in vitro and in vivo." (PMID 38002059, 2023). "Sirtuin 1 (silent mating type information regulation 2 homolog, SIRT1) is a NAD(+)-dependent histone deacetylase linking metabolism and survival signaling in cancer." (PMID 37816710, 2023). "SIRT6 and SIRT1 enhance the enzymatic NADPH activity by direct deacetylation of the protein, protecting cancer cells from oxidative stress." (PMID 37175631, 2023). "To date, such molecular pathways are known that regulate the expression and activity of NAMPT in cancers, such as c-MYC/NAMPT/SIRT1, HMGA1/NAMPT/NAD+, FOXO1/NAMPT, NAMPT/miRNA, SIRT6/SIRT1/NAMPT, C/EBPβ/NAMPT." (PMID 37175631, 2023). "Studies investigating SIRT1/vitamin D/FOXO interaction suggest a link between VDR, SIRT1, and FOXO3 function, and provide a molecular basis for the cancer chemoprevention actions of 1,25(OH2)D3." (PMID 37047134, 2023). "GAS5 is a newly discovered lncRNA that exerts inhibitory effects through the modulation of several target microRNAs in cancer, and miR-34a acts as a tumor-suppressor gene in human CRC by blocking autophagy through sirtuin 1 (SIRT1) regulating." (PMID 37373349, 2023). "Sirtuin‐1 (SIRT1) is an important NAD + ‐dependent histone deacetylase in mammals, and participates many biological processes in cancer." (PMID 36510377, 2023). "SIRT1, in particular, demonstrates a dual role in HNSCC, with lowered expression in cancer cells and a potential contribution to chemoresistance." (PMID 38203666, 2023). "NAD+‐dependent HDACs such as SIRT1 and SIRT3 trigger ferroptosis induction by inhibiting EMT markers in cancer cells." (PMID 37229485, 2023). "Cancer cell growth is primarily facilitated by the EMT marker proteins e-cadherin and vimentin, and SIRT1 is connected to the production of invasive proteins in tumors." (PMID 36899911, 2023). "SIRT1 contributes to chromatin remodeling and VEGF promotes angiogenesis which in turn promotes the progression of cancer." (PMID 36225477, 2022). "Many studies are showing that SIRT1/PGC-1α/Nrf2 signaling can regulate both pyroptosis and oxidative stress in different situations such as cancer or liver oxidative stress." (PMID 35355717, 2022). "In the PPI network, the core targets, including AKT1, CREB1, CDC42, SIRT1, PIK3CA, and MMP9, are key cancer‐related genes, which further indicate the important role of miR‐204‐5p in human cancers." (PMID 35908280, 2022). "It is known that resveratrol is a sirtuin 1 activator, represented by the SIRT1 gene, improving mitochondrial function and slowing the proliferation of certain cancers." (PMID 36296673, 2022). "On the other hand, SIRT1 enhances HIF-2α activity through its deacetylase activity, inhibiting cancer metastasis formation." (PMID 35745656, 2022).
cancer (continued). "MiR-34a was largely reported to be a tumor suppressor via silencing multiple OS-related oncogenes and signaling pathways, including SIRT1, IGF2BP3, FOXM1/eEF2K and IL-6R/STAT3 signaling axis, regulated cancer drug resistance, growth and metastasis." (PMID 35081965, 2022). "SIRT1 is the most studied enzyme in the SIRT family and is known to regulate cell proliferation, apoptosis, differentiation, migration, and invasion of cancer cells." (PMID 35163511, 2022). "Therefore, SIRT1 overexpression may inhibit the proliferation of cancer cells." (PMID 35855334, 2022). "SIRT1 (sirtuin 1) is an NAD+-dependent deacetylase that plays key roles in biological responses, including aging, cancer, glucose metabolism, and energy homeostasis." (PMID 35889833, 2022). "Sirtuin 1, known as NAD-dependent deacetylase sirtuin-1, promoted cancer cell proliferation and metastasis via STAT3/MMP-13 signaling, which is also found participated in the abnormal metabolism pathways in AML." (PMID 36727051, 2022). "Validated targets of miR-9-5p are BCL6, a nuclear protein with transcriptional repressor activity, and SIRT1, a class III histone deacetylase having multiple functions in cancer progression." (PMID 36293105, 2022). "Mammalian sirtuins SIRT1 and SIRT6 have been demonstrated to control circadian rhythms as well as metabolism, aging, and cancer." (PMID 34834402, 2021). "Among all members of the sirtuin family, SIRT1 and SIRT2 have been extensively studied due to their prominent role in cancer cell fate." (PMID 34445277, 2021). "Sirtuin 1 (Sirt1) is a nicotinamide adenine dinucleotide (NAD)-dependent deacetylase that is a member of the HDAC family and participates in cancer-related epigenetic regulation by catalyzing the deacetylation of histones and non-histone proteins." (PMID 33806538, 2021). "Interestingly, SIRT1 can promote the acquisition of stem cell characteristics in tumor cells, and these cells can become resistant to chemotherapy, radiation, and target drugs, and plays a key role in malignant progression of tumors, tumor metastasis, and cancer recurrence." (PMID 34381712, 2021). "Earlier works have found that the unusual quantity of SIRT1 and SIRT2 were related to a wide range of malignant tumors." (PMID 33705642, 2021). "Sirtuin 1 (SIRT1), an NAD+-dependent deacetylase, is a crucial regulator that produces multiple physiological benefits, such as the prevention of cancer and age-related diseases." (PMID 33608631, 2021). "The silent information regulators SIRT1 and SIRT3 are members of thesirtuins protein family known to be involved in cancer genetics, aging and oxidative stress responses." (PMID 33687167, 2021). "The high levels of collagen I, C-MYC, SIRT1, COX2, and RAD51 expression in the tumor are attenuated by the treatment, leading to reduced fibrosis, viability, inflammation, culminating in cancer cell death." (PMID 34959644, 2021). "In summary, our analyses show that SIRT1 and CUL4B are upregulated in multiple carcinomas and are potential cancer biomarkers." (PMID 34163012, 2021). "The correlation between the expression of SIRT1 and lncRNA PP7080 or miR-601 in the cancer tissues of 40 cancer patients was analyzed." (PMID 33955831, 2021). "Thus, the role of SIRT1 in cancer may vary depending on the context." (PMID 34650436, 2021). "A study of the correlation between SIRT1 and the clinical characteristics of NSCLC patients revealed that SIRT1 tends to be highly expressed in poorly differenced cancers, indicating that it plays a tumorigenic role in NSCLC." (PMID 34381712, 2021). "Next, we used Gene Expression Profiling Interactive Analysis to analyze SIRT1 and CUL4B expression profiles in The Cancer Genome Atlas tumor samples and corresponding normal tissues." (PMID 34163012, 2021).
cancer (continued). "The impacts of resveratrol signaling on structural integrity, colonosphere formation and invasion, prominent features of cancer in TNF-β or in multicellular-TME and/or Sirt1-ASO were evaluated in 3D-alginate HCT116 cells." (PMID 32962102, 2020). "SIRT1 positively regulates the expression of ABC transporters, such as MDR1 and ABCA1, which promote efflux of anti-cancer drugs from cells." (PMID 32151067, 2020). "Sirtuin 1 (SIRT1) belongs to the family of NAD+-dependent deacetylases, and its protective role in cancers, vascular diseases, and aging is well-known (38, –, 40)." (PMID 31932306, 2020). "Sirtuin 1 (SIRT1) is one of the early studied members of sirtuin family and is considered as a key regulator of various biological processes, especially in cancer." (PMID 32714081, 2020). "On the contrary, higher level of HDACs such as SIRT1, SIRT2, and SIRT7 were detected in cancer cells." (PMID 33262941, 2020). "Sirtuin‐1 (SIRT‐1) is a family member of NAD+‐dependent histone deacetylases, which has been shown to regulate cancer cells' metabolism, cell cycle, and metastasis (Liu, Zangeneh, Zangeneh, & Guo, 2020; Zhou, Yang, & Li, 2019)." (PMID 33133558, 2020). "An in vitro model with 3D-alginate HCT116 cells in multicellular-TME cultures (fibroblast cells, T-lymphocytes) was used to elucidate the role of TNF-β, Sirt1-ASO and/or resveratrol in the proliferation, invasion and cancer stem cells (CSC) of CRC cells." (PMID 32962102, 2020). "Increasing evidence suggests that sirtuin 1 (SIRT1), a class III histone deacetylase (HDAC), plays critical roles in multiple aspects of cancer drug resistance." (PMID 32398958, 2020). "In line with the results for cancer cell lines, HKC-8 normal kidney cell line exposed to 20 mM lactate displayed reduced SIRT1 transcript and protein levels, as well as global sirtuin activity reduction." (PMID 32340156, 2020). "Both the stress-response protein, SIRT1, and the cell cycle checkpoint kinase, CHK2, play critical roles in aging and cancer via the modulation of cellular homeostasis and the maintenance of genomic integrity." (PMID 31209362, 2020). "Several bioactive food components are known to activate SIRT1, a nicotinamide adenine dinucleotide (NAD+)-dependent deacetylases (class III) involved in various cellular processes from aging to cancer." (PMID 32878301, 2020). "The mammalian sirtuins (SIRT1-7) are NAD+-dependent lysine deacylases with central effects in cell survival, inflammation, energy metabolism, cancer, aging, cardiovascular disorders and neurodegeneration." (PMID 30871086, 2019). "Under oxidative stress, for example during certain cancer treatments, CHK2 dissociates from SIRT1, and its enzymatic activity is increased." (PMID 30902968, 2019). "Recent studies confirmed that the expression of SIRT1, a class III histone deacetylase, regulates the migration of various cancer cells in vitro and tumor metastasis in vivo, including in hepatocellular carcinoma, colorectal cancer, and gastric cancer." (PMID 31133857, 2019). "A number of epigenetic therapies such as SIRT1 inhibitors, HDAC inhibitors and EZH2 inhibitors are currently in clinical trials for many cancer indications, and have shown promise in murine models and good safety profiles in Phase I healthy individuals." (PMID 31380371, 2019). "In contrast, splitomicin analogs have shown activity against SIRT1 and SIRT2 as well as antiproliferative properties in cancer cells." (PMID 30761005, 2019). "The protein Deleted in Breast Cancer-1 is a regulator of several transcription factors and epigenetic regulators, including HDAC3, Rev-erb-alpha, PARP1 and SIRT1." (PMID 31591441, 2019).